DAAM1 (dishevelled associated activator of morphogenesis 1)
Diseases named in the same sentence as DAAM1 in open-access papers (continued):
Sharing a sentence is not in itself a finding about the gene and the disease.
metastatic tumor (1 paper, 2019). "In view of a fact that DAAM1 showed the increased expression and activation level in lymphnode metastatic tumor tissues, we speculated that the regulation of genomic and/or transcriptional level may be heterogeneous in individual BrCa tissues." (PMID 30911286, 2019). "Expression analysis demonstrate that miR-208a-5p is significantly suppressed in lymphnode metastatic tumor samples than that in non-lymphnode metastatic tumor samples, indicating the potential role of miR-208a-5p on anti-tumor metastasis via DAAM1 signaling." (PMID 30911286, 2019). "We found that both the expression and the activation of DAAM1 in lymphnode metastatic tumor tissues were significantly higher than these in non-lymphnode metastatic tumor tissues." (PMID 30911286, 2019).
non-small cell lung carcinoma (1 paper, 2016). A group of at least three distinct histological types of lung cancer, including non-small cell squamous cell carcinoma, adenocarcinoma, and large cell carcinoma. "The DAAM1-NC mutant created actin meshwork with short filaments in the cell lines tested in this study, including MEFs, human foreskin fibroblast (HFFs), HeLa JW cell line, and the H460 non-small cell lung cancer cell line that is deficient of DAAM1." (PMID 27760153, 2016).
pulmonary arterial hypertension (1 paper, 2017). Pulmonary arterial hypertension (PAH) is a group of diseases characterized by mean pulmonary artery pressure >20 mmHg and elevated pulmonary arterial resistance leading to right heart failure. "In addition, Dvl-2 was depleted while Daam-1 expression was elevated in IPAH, in contrast with specimens from associated pulmonary arterial hypertension cases and controls." (PMID 28288669, 2017).
Salmonella Infections (1 paper, 2021). Infections with bacteria of the genus SALMONELLA. "Apart from PPARδ, the work identifies new targets of KDM6B demethylase activity in the host upon Salmonella infection such as CSNK1D and DAAM1." (PMID 34696686, 2021).
spina bifida (1 paper, 2019). A congenital neural tube defect in which vertebrae are not fully formed. "Conditional mosaic deletion of the mammalian core PCP component Vangl2, or compound heterozygous mutations of Vangl2 and the Diaphanous-related formin Daam1, lead to spina bifida." (PMID 31182644, 2019).
triple-negative breast carcinoma (1 paper, 2019). An invasive breast carcinoma which is negative for expression of estrogen receptor (ER), progesterone receptor (PR), and human epidermal growth factor receptor 2 (HER2). "miR-613 inhibits cell migration and invasion by downregulating Daam1 in triple-negative breast cancer." (PMID 31019537, 2019).
cancer (16 papers, 2019 to 2025). A tumor composed of atypical neoplastic, often pleomorphic cells that invade other tissues. "Of note, Daam1 has been associated with cancer progression in other tissues." (PMID 33869179, 2021). "The effects of non-coding mutations on MTG2 transcription have been summarized in various cancer cell lines, and increased expression of DAAM1 leads to aggressive cell migration." (PMID 40544380, 2025). "Several Formins (including DAAM1 and DAAM2) are key components of canonical WNT signaling in cancer development, thus they are involved in APC mutation and colon polyp formation." (PMID 37249599, 2023). "In the current research, we analyzed the expressions and prognostic values of DAAM1 across cancer types and focused on the immuno‐correlation of DAAM1 in kidney renal clear cell carcinoma (KIRC)." (PMID 36311172, 2022). "Emerging evidence has uncovered that DAAM1 functions as a critical oncogene in facilitating tumor metastasis of multiple cancers." (PMID 36311172, 2022). "Firstly, we explored the levels of DAAM1 mRNA expression in multiple tumor types using the RNA‐sequencing data from The Cancer Genome Atlas (TCGA) dataset." (PMID 36311172, 2022). "Dishevelled-associated activator of morphogenesis 1 (DAAM1) is a classical actin-associated protein and mediates the polymerization of microfilament, regulating vertebrate gastrulation and cancer metastasis." (PMID 34453038, 2021). "However, high DAAM1 expression was associated with well prognosis in KIRC, which was inconsistent with its oncogenic roles in most cancers." (PMID 36311172, 2022). "Besides, DAAM1 is found to be upregulated in CD133 + cancer stem cells, suggesting its critical role in the maintenance of tumor cell stemness." (PMID 34453038, 2021). "To assess whether rs79036859 A/G was related to DAAM1 expression in clinical samples, we detected DAAM1 mRNA levels in cancer tissues using quantitative PCR in 157 cases and examined DAAM1 protein expression by IHC in 46 patients." (PMID 30911286, 2019). "Indeed, the actin bundling factor Daam1 and L-plastin were shown to functionally cooperate with Fascin-1 in the stabilization of invadopodia and filopodia in cancer cells." (PMID 30654764, 2019). "Besides, compared with the results of the differential analysis, our results showed that most of dynamic network biomarkers identified by node entropy, such as NKD2 or DAAM1, located in upstream in many important cancer-related signaling pathways regulated intergenic signaling within pathways." (PMID 32766227, 2020). "At the same time, we found DAAM1 and NKD2 gene, two of our hub genes involved in Wnt pathway, worked as intermediate elements in signal regulation across different cancer." (PMID 32766227, 2020). "The mRNA and protein level of DAAM1 was significantly decreased in miR-208a-5p-overexpressed in MCF-7 and MDA-MB-231 cells, but upregulated in miR-208a-5p inhibitor-overexpressed cancer cells." (PMID 30911286, 2019). "More importantly, deregulation of genes in this module including PLK4, AURKB, DAAM1 and DAAM2 are correlated with aggressive forms of human cancer." (PMID 31142743, 2019). "In the same type of cells, Fascin-1 was shown to interact with the non-canonical Wnt/PCP downstream target Daam1, promoting cancer cell migration." (PMID 37015875, 2023). "With regard to the prognostic values of DAAM1 in different cancers, we found that they were not significant in most cancer types." (PMID 36311172, 2022). "However, the systematic analysis of the role of DAAM1 in pan‐cancer has not been observed." (PMID 36311172, 2022).
cancer (continued). "Cell morphology and p-MLC2 levels were assessed as amoeboid markers; ki-67 staining as a proliferative marker; WNT11, WNT5B and DAAM1 expression as non-canonical Wnt markers; and ALDH1A1, ALDH1A3, CD44, NANOG and OCT4 were evaluated as cancer stem cell-related markers." (PMID 33082334, 2020). "Furthermore, the KEGG pathway enrichment analysis of tRF-1:28-Val-CAC-2 was enriched in pathways in cancer, which included the Hedgehog signaling pathway with EVI1, BCL2, and PKA and the Wnt signaling pathway (not in the top 10) with Frizzled, Daam1, and NFAT." (PMID 34988117, 2021).
tumor (13 papers, 2011 to 2025). "This interaction leads to cytoskeletal remodeling, protrusion formation, and enhanced motility of tumor cells, demonstrating a novel polycystin‐1/Daam1‐dependent mechanotransduction axis." (PMID 40789101, 2025). "Polycystin‐1 (PC1) senses collagen and ECM stiffness to promote tumor migration via Daam1‐mediated actin remodeling." (PMID 40789101, 2025). "Collectively, our findings identify polycystin‐1 as a mechanosensor of collagen and ECM stiffness that modulates tumor cell migration via the Daam1/RhoA/YAP signaling cascade." (PMID 40789101, 2025). "In this research, we report that DAAM1 is downregulated in tumor tissues and predicts well prognosis." (PMID 36311172, 2022). "We checked the correlations between DAAM1 expression and tumor‐infiltrating lymphocytes in KIRC and the results showed that DAAM1 was positively correlated with the levels of CD8+ T cell, CD4+ T cell, macrophage, neutrophil, and dendritic cell." (PMID 36311172, 2022). "In addition, immortalized tumor cell lines were reported to express Fscn1 and have frequently been used to as cell models to delineate the interaction of Fscn1 with other cytoskeletal proteins, such as cofilin-1 and Daam1 (disheveled-associated activator of morphogenesis 1), among others." (PMID 35681718, 2022). "Studies have found that reducing the protein level of DAAM1 can efficiently suppress tumor cell colony formation, invasion, and migration." (PMID 35719372, 2022). "Studies have shown that miR-208a-5p, miR-34a-5p, and miR-188-5p notably inhibit DAAM1 expression and participate in tumor suppression." (PMID 34453038, 2021). "Our previous studies find that active DAAM1 is elevated by the treatment of Wnt5a or type IV collagen and participates in the tumor cell migration and haptotaxis." (PMID 30911286, 2019). "The results showed that DAAM1 mutant tumor tissues (AG/GG genotypes) expressed higher levels of DAAM1 mRNA and protein than DAAM1 wildtype tumor tissues (AA genotype)." (PMID 30911286, 2019). "For instance, collagen regulates the extension of invadopodia through the integrin αvβ3/Dishevelled-associated activator of morphogenesis 1 (DAAM1)/Ras Homolog family member A (RHOA)-dependent cascade, which are small actin-rich protrusions that mediate the invasion of tumor cells." (PMID 39769286, 2024). "Besides, compared with para-tumor tissues, the expression levels of DAAM1 and YWHAZ were both upregulated in BrCa tissues, which was in accord with previous research." (PMID 34453038, 2021). "However, it is still limited evidence demonstrating that DAAM1 is correlated with tumor metastasis in BrCa patients." (PMID 30911286, 2019). "We further examined whether Daam1 abrogation counteracts the anti-tumor effects of antagomir-335." (PMID 21592405, 2011). "These included well-known receptor tyrosine kinase genes (EGFR, TEK and OSMR) that activate MAPK and PI3K signaling pathways, and other tumor-promoter genes (ATP8B2, DAAM1, SLAMF8 and SRGN) as well as tumor-suppressor genes (A2M, DAPK1, RASSF8 and SOCS3)." (PMID 37190308, 2023). "FOXD3 mRNA and protein expression and miR-335 expression were upregulated while DAAM1 mRNA and protein expression along with extent of MLC2 phosphorylation was reduced in tumor tissues of mice co-treated with oe-FOXD3 and CP." (PMID 36627652, 2023). "As a novel partner of DAAM1, YWHAZ has been demonstrated to highly express in BrCa tissues and regulate the malignant phenotypes of tumor cells." (PMID 34453038, 2021). "DAAM1 depletion yielded a reduction in TIF and a decrease in tumour growth at limiting dilutions of 50,000 and 5,000 cells." (PMID 33082334, 2020). "To further verify the potential effect of the DAAM1 3′-UTR SNP rs79036859 in BrCa, we performed a case-based method to assess the function of rs79036859 in tumor metastasis." (PMID 30911286, 2019).
tumor (continued). "Moreover, DAAM1 can activate Rho-ROCK1/2-myosin II and thus plays pivotal roles in modulating tumor-initiating potential and local invasion as well as distant metastasis." (PMID 36627652, 2023). "Moreover, the positive correlation of DAAM1 and YWHAZ was observed not only in BrCa tissues but in most tumor and normal tissues." (PMID 34453038, 2021). "DAAM1 depletion led to a reduction in TIF and in A375M2 tumour growth." (PMID 33082334, 2020). "When we compared DAAM1 mRNA expression in lymphnode metastatic tumor tissues and non-lymphnode metastatic tumor tissues along with distance metastatic tumor tissues and non-distance metastatic tumor tissues, the expression of DAAM1 mRNA was significantly increased in metastatic tissues." (PMID 30911286, 2019).
infection (2 papers, 2018 to 2021). The state of being infected such as from the introduction of a foreign agent such as serum, vaccine, antigenic substance or organism. "The role of human Daam1 protein to mediate coiling phagocytic activity was examined by treating the H4 and HS683 cells with anti-Daam1 antibody prior to infection with GFP-expressing WT B. burgdorferi." (PMID 29746581, 2018). "We showed that binding of BBA66 and Daam1/FH2 occurred with recombinant proteins, therefore our next aim was to demonstrate binding of the native proteins by B. burgdorferi cell infections in vitro." (PMID 29746581, 2018). "When using the BBA66-expressing strains in neuroglial cell infections, we observed apparent colocalization between BBA66 and Daam1 when borrelia were being captured by pseudopodia." (PMID 29746581, 2018).
DAAM1 also shares sentences with these, for which no sentence is quoted: clear cell renal cell carcinoma (1 paper); Cognitive impairment (1); colon polyp (1); colorectal cancer (1); craniorachischisis (1); glioblastoma (1); liposarcoma (1); malignant peripheral nerve sheath tumor (1); microphthalmia (1); nasopharyngeal carcinoma (1); neurodevelopmental disorder (1); osteosarcoma (1); round cell liposarcoma (1); SARS-CoV infection (1); Sertoli Cell-Only Syndrome (1); testicular diseases (1).